CLCN3 (Cl-/H+ antiporter 3)
Description:
[Isoform 1]: Strongly outwardly rectifying, electrogenic H(+)/Cl(-)exchanger which mediates the exchange of chloride ions against protons (By similarity). The CLC channel family contains both chloride channels and proton-coupled anion transporters that exchange chloride or another anion for protons. The presence of conserved gating glutamate residues is typical for family members that function as antiporters. [Isoform 2]: Strongly outwardly rectifying, electrogenic H(+)/Cl(-)exchanger which mediates the exchange of chloride ions against protons.
Synonyms: ClC-3; CLC3; NEDHYBA; NEDSBA
Tractability: Small molecule: it belongs to a druggable protein family. Antibody: its Gene Ontology location is reachable by antibodies, with high confidence; UniProt places it where antibodies can reach, with medium confidence; UniProt predicts a signal peptide or a membrane-spanning region. PROTAC: ubiquitination databases record sites on it; its protein half-life has been measured.
Target class: Chloride channel; ClC chloride channel; Other ion channel; Ion channel
Gene: Protein-coding gene on chromosome 4 (169,612,438 to 169,723,673, forward strand). Ensembl gene ENSG00000109572.
Subcellular location: Early endosome membrane (Isoform 1); Late endosome membrane; Lysosome membrane; Cell membrane; Golgi apparatus membrane (Isoform 2); Cell projection, ruffle membrane
Subcellular location (Human Protein Atlas): Vesicles
Pathways (Reactome):
Transport of small molecules: Stimuli-sensing channels
Gene Ontology:
Molecular function: chloride channel activity; PDZ domain binding; protein binding; volume-sensitive chloride channel activity; antiporter activity; voltage-gated chloride channel activity; chloride transmembrane transporter activity; chloride:proton antiporter activity
Biological process: chloride transmembrane transport; negative regulation of cell volume; endosomal lumen acidification; chloride transport; proton transmembrane transport; transmembrane transport
Cellular component: cytoplasmic vesicle; early endosome; early endosome membrane; external side of plasma membrane; GABA-ergic synapse; glutamatergic synapse; Golgi apparatus; Golgi membrane; late endosome; late endosome membrane; membrane; phagocytic vesicle; plasma membrane; secretory granule; specific granule; synaptic vesicle; synaptic vesicle membrane; vesicle membrane; cell surface; endoplasmic reticulum membrane; endosome membrane; lysosomal membrane; recycling endosome; ruffle membrane
Genetic constraint (gnomAD): Loss-of-function variants: 13 observed, 60.58 expected, observed/expected ratio (o/e) 0.21, 90% interval 0.14 to 0.34. The upper end of that interval is the gene's LOEUF score, 0.34, which puts it in group 1 of 6, group 1 being the genes least tolerant of losing a copy. Missense variants: 457 observed, 879.73 expected, observed/expected ratio (o/e) 0.52, 90% interval 0.48 to 0.56. Synonymous variants: 266 observed, 300.26 expected, observed/expected ratio (o/e) 0.89, 90% interval 0.8 to 0.98.
Homologues: Orthologues: chimpanzee CLCN3 (98% identical), macaque CLCN3 (98% identical), rabbit CLCN3 (98% identical), guinea pig CLCN3 (98% identical), dog CLCN3 (97% identical), mouse Clcn3 (97% identical), pig CLCN3 (97% identical), rat Clcn3 (97% identical), zebrafish clcn3 (88% identical), tropical clawed frog clcn3 (88% identical), Drosophila melanogaster ClC-c (59% identical), Caenorhabditis elegans clh-5 (52% identical). Paralogues in human: CLCN5 (72% identical), CLCN4 (71% identical), CLCN7 (28% identical), CLCN6 (27% identical), CLCN2 (25% identical), CLCN1 (23% identical), CLCNKA (20% identical), CLCNKB (20% identical).
Diseases named in the same sentence as CLCN3 in open-access papers:
CLCN3 is named in the same sentence as 93 diseases in open-access papers, as found by Europe PMC text mining. Sharing a sentence is not in itself a finding about the gene and the disease. The quoted sentences say what the papers report.
glioma (33 papers, 2011 to 2025). A benign or malignant brain and spinal cord tumor that arises from glial cells (astrocytes, oligodendrocytes, ependymal cells). "Recently, it was demonstrated a decrease in lysosome stabilization induced by CLCN3 (chloride voltage-gated channel 3) suppression in glioma U251 cells treated with cisplatin." (PMID 32429050, 2020).
breast cancer (10 papers, 2015 to 2025). A primary or metastatic malignant neoplasm involving the breast. "Encouragingly, the top resistance gene hit, CLCN3 (shRNA depleted 4.45‐fold), encodes for transporter chloride channel 3 and is a known mediator of multidrug resistance, including paclitaxel and docetaxel resistance in breast cancer cells." (PMID 33932086, 2021). "Spontaneous mammary cancer with ClC-3 overexpression in MMTV-PyMT/CLCN3 double transgenic female mice used in this research showed drug resistance to PTX and DOX that led to a significant decrease in survival times." (PMID 35054564, 2021). "Our findings in this study demonstrated that CLCN3 is a potential direct target of miR-205-5p and regulates 3D spheroid proliferation in ErbB2-overexpressing breast epithelial cells and breast cancer cells." (PMID 31608175, 2019). "Since our data indicated that CLCN3 is one of the potential targets of miR-205-5p, we investigated the possible biological function of CLCN3 in ErbB2-overexpressing breast epithelial cells and breast cancer cells." (PMID 31608175, 2019). "Interestingly, we additionally found that miR-205-5p expression was significantly reduced in the ErbB2-overexpressing breast cancer cell lines stably expressing CLCN3 shRNA." (PMID 31608175, 2019). "In addition, we established CLCN3 shRNA or control shRNA stably expressing cells using the ErbB2-overexpressing breast cancer cell lines SKBR3 and MDA-MB-453 and analyzed the 3D spheroid proliferation of these stable cells." (PMID 31608175, 2019). "To understand the comprehensive role of miR-205-5p in breast cancer, we attempted to identify a novel target of miR-205-5p that may be involved in breast cancer progression and performed analyses focusing on CLCN3." (PMID 31608175, 2019). "Collectively, these novel findings suggest that CLCN3 may be a novel direct target of miR-205-5p and this CLCN3/miR-205-5p interaction may serve a pivotal role in regulating breast cancer cellular proliferation under physiological conditions." (PMID 31608175, 2019). "On the basis of these observations, CLCN3 may have the potential to be a novel therapeutic target for ErbB2-overexpressing breast cancers." (PMID 31608175, 2019). "Three ion channel genes KCNK1, CLCN3, and CACNB3, which were overexpressed in breast cancer, and another ion channel gene ANO6, which was underexpressed in breast cancer, were identified by significance analysis of microarrays (SAM)." (PMID 38905316, 2024). "To assess the roles of CLCN3 in breast cancer, we next performed three-dimensional (3D) spheroid proliferation analyses using MCF10A-ErbB2 cells treated with MCF10A-neo-derived exosomes or CLCN3 shRNA stably expressing SKBR3 and MDA-MB-453 breast cancer cells." (PMID 31608175, 2019). "However, the roles of CLCN3 in breast cancer cell proliferation remain unclear." (PMID 31608175, 2019). "In contrast, the expression of CLCN3, CACNB3, and ANO6 in breast cancer did not correlate significantly with patient prognosis." (PMID 38905316, 2024).
glioblastoma (9 papers, 2011 to 2025). The most malignant astrocytic tumor (WHO grade IV). "Interestingly, expressions of MMP2, chloride voltage-gated channel 3 (CLCN3), and annexin A3 (ANXA3) seem to be indispensable for the binding of CLTX to glioblastoma cells." (PMID 36721153, 2023).
schizophrenia (8 papers, 2019 to 2023). A major psychotic disorder characterized by abnormalities in the perception or expression of reality. "Moreover, we identified evidence to support previously implicated targets, such as CLCN3 (schizophrenia, P = 5.99 × 10−7), which have been reported to play a role in the control of glutamatergic transmission." (PMID 33481009, 2021). "Dysregulation of the genes FURIN, TSNARE1, CNTN4, CLCN3 and SNAP91 have been implicated by eQTL analysis of schizophrenia GWAS hits, which were later separately prioritized by chromatin interaction analysis of schizophrenia risk variants." (PMID 35972862, 2022). "Large-scale genome-wide association studies (GWAS) have identified a set of common genetic variants in glutamatergic genes in patients with schizophrenia, including, for instance, GRM3, GRIN2A, GRIA1, SRR, CLCN3, among others." (PMID 31431615, 2019).
myocardial hypertrophy (5 papers, 2014 to 2025). "The inactivation of the Clcn3 gene causes severe myocardial hypertrophy and heart failure in knockout mice." (PMID 24744906, 2014). "For example, Clcn3 (chloride channel/antiporter) is directly targeted by miR-1-3p, and heart-specific inducible Clcn3 knock-out mice develop myocardial hypertrophy and reduced cardiac function." (PMID 40725017, 2025). "A previous study showed that the deletion of Clcn3 potentially affects the ion channel involved in cell volume homeostasis, which likely drives the development of myocardial hypertrophy and heart failure." (PMID 33168059, 2020). "Heart- specific inducible Clcn3 knock-out mice produced myocardial hypertrophy and significantly reduced cardiac function (marked shortening of LVEF and significant increasing in LV chamber cavity) compared with control mice." (PMID 29885652, 2018). "Many studies have demonstrated Clcn3 plays an important role in cardiac and vascular remodeling during myocardial hypertrophy." (PMID 29885652, 2018). "We also confimed Clcn3 as a direct target of miR-1-3p which may provide novel therapeutic tools for the treatment of myocardial hypertrophy." (PMID 29885652, 2018).
retinal degeneration (4 papers, 2018 to 2025). Degeneration of the retina. "Pathogenic CLCN3 variants in humans result in clinical features such as intellectual disability, seizure, severe neuropsychiatric disorders, brain abnormality, and hippocampal and retinal degeneration with delayed gross and fine motor development." (PMID 41023377, 2025). "Clcn3−/− mice show hippocampal and retinal degeneration, recapitulating key symptoms observed in humans." (PMID 41023377, 2025).
epilepsy (3 papers, 2022 to 2025). A brain disorder characterized by episodes of abnormally increased neuronal discharge resulting in transient episodes of sensory or motor neurological dysfunction, or psychic dysfunction. "Currently, mutations in the CLCN1, CLCN2, CLCN3, CLCN4, and CLCN6 genes have been reported to be associated with various forms of epilepsy." (PMID 40223930, 2025). "However, to date, no pathogenic mutations have been reported in the CLCN3 gene in patients with epilepsy." (PMID 40223930, 2025).
Obesity (3 papers, 2023 to 2024). Accumulation of substantial excess body fat. "There is not yet sufficient research evidence and definitive understanding that Clcn3 deficiency directly ameliorates obesity and its’ possible mechanism." (PMID 38784133, 2024). "Modulation of Clcn3 may provide an appealing therapeutic target for obesity and associated metabolic syndrome." (PMID 38784133, 2024). "RNA-seq and Western blotting indicated that Clcn3 deficiency may inhibit obesity through the AMPK-UCP1 axis." (PMID 38784133, 2024). "In conclusion, Clcn3 deficiency ameliorates HFD-induced obesity, meanwhile, improves glucolipid metabolism disorders, and the impairment of insulin sensitivity, which may be because of the AMPK-Ucp1 axis." (PMID 38784133, 2024). "The western blotting indicated that Clcn3 deficiency may inhibit obesity through the AMPK-UCP1 axis, which could become a potential target for improving metabolic dysfunction and obesity." (PMID 38784133, 2024). "To verify the relationship between the Clcn3 and weight including metabolic changes, searching for a new target for metabolic therapy of obesity, we designed the experiment." (PMID 38784133, 2024). "Functionally, CLCN3 is considered to be instrumental and indispensable in the control of inflammation of adipose tissue and obesity in mammals, and therefore, it has been useful in the therapeutic treatment of type 2 diabetic patients and obesity." (PMID 39336754, 2024). "Increase of UCP1 in the WAT of Clcn3 knockout mice, suggesting that UCP1 may be a target for Clcn3 deficiency to prevent obesity." (PMID 38784133, 2024). "Clcn3 may be an early contributor to the development of obesity." (PMID 38784133, 2024). "Consequently, the knockout of Clcn3 may facilitate WAT browning to ameliorate obesity-related effects and subsequent metabolic dysfunction." (PMID 38784133, 2024).
developmental delay (2 papers, 2023 to 2025). "CLCN3 encodes ClC-3, an endosomal 2Cl−/H+ exchanger, with pathogenic variants causing a neurodevelopmental condition marked by developmental delays, intellectual disability, seizures, hyperactivity, anxiety, and brain and retinal abnormalities." (PMID 41023377, 2025). "LOF of ClC-3 in mice leads to neurodegeneration and both GOF and LOF CLCN3 variants in humans cause severe global developmental delay." (PMID 36385166, 2023).
Failure to thrive (2 papers, 2023 to 2025). Failure to thrive (FTT) refers to a child whose physical growth is substantially below the norm. "LARP7, an interacting protein of CLCN3 at the protein level, has been reported as a causative of Alazami syndrome characterized by failure to thrive, short stature, and DD symptoms." (PMID 38025430, 2023).
lung adenocarcinoma (2 papers, 2015 to 2022). A carcinoma that arises from the lung and is characterized by the presence of malignant glandular epithelial cells. "The role of CLCN3 in lung adenocarcinoma (LUAD) is unexplored and the relationship between CLCN3 and tumor microenvironment is unknown." (PMID 36439880, 2022).
neuropathies (2 papers, 2021 to 2025). "Activating CLCN7 mutations can cause vacuolization in patients’ tissues, but it is unclear whether this occurs in CLCN3 or CLCN4 neuropathy patients whose mutations we have analyzed here." (PMID 40169677, 2025).
osteosarcoma (2 papers, 2016 to 2025). A usually aggressive malignant bone-forming mesenchymal neoplasm, predominantly affecting adolescents and young adults. "In our study, CLCN3 was hypomethylated in metastatic GISTs, which likely correlates with increased gene expression, aligning with findings in chondrosarcoma and osteosarcoma." (PMID 40145859, 2025).
autism spectrum disorder (1 paper, 2023). A spectrum of developmental disorders that includes autism, and Asperger syndrome. "In summary, our study has revealed the involvement of four known genes (DEAF1, CLCN3, KMT2C, and DHX30) as well as two novel genes (TRPC4 and SCFD2) in autism spectrum disorder across six families from Qatar." (PMID 38025430, 2023).
Bestrophinopathy (1 paper, 2017). "We found the same dialysis activated Cl- currents in bone marrow derived neutrophils from CLIC1, CLCN3, CLCN7 and KCC3 KO animals and in blood neutrophils from a Bestrophinopathy patient (Best1 H178P) (representative current traces)." (PMID 28553230, 2017).
cystic fibrosis (1 paper, 2020). Autosomal recessive disorder caused by pathogenic variants in the CFTR gene (cystic fibrosis transmembrane conductance regulator), which encodes a chloride and bicarbonate channel expressed in epithelial cells, and follow the diagnosis criteria. "Chloride voltage-gated channel 3 (CLCN3) is a protein coding gene which is associated with cystic fibrosis." (PMID 32366026, 2020).
galactosemia (1 paper, 2017). "Galactosemia caused the osmotic stress in lenses; it also markedly leads to the upregulations of AR, P-gp, and Clcn3 in LECs, together resulting in obvious osmotic expansion in vitro and in vivo." (PMID 29527534, 2017). "Although Clcn3 and P-gp expressed faintly in normal lens anterior capsules under physiological condition, both were predominantly upregulated in galactosemia, and the early stage was a key period of lens osmotic expansion." (PMID 29527534, 2017). "In conclusion, AR was overactivated by galactosemia and led to severe osmotic expansion in lenticular cells; subsequently, P-gp and Clcn3 were both upregulated due to lenticular cell swelling and tried to maintain the osmotic balance within galactosemic lenses." (PMID 29527534, 2017).
hypertrophic cardiomyopathy (1 paper, 2020). A condition in which the myocardium is hypertrophied without an obvious cause. "The direct target of miR-1-3p is probably chloride voltage-gated channel 3 (Clcn3), which clarifies the mechanism of hypertrophic cardiomyopathy." (PMID 31973111, 2020).
lentivirus infection (1 paper, 2015). Virus diseases caused by the Lentivirus genus. "To understand the importance of increased ClC-5 expression in MSC cultured from ClC-3 mice we applied shRNA via lentivirus infection to reduce ClC-5 expression in bone-forming cultures from Clcn3−/− mice, and characterized the resulting bone differentiation." (PMID 26603451, 2015).
lipid metabolism disorder (1 paper, 2024). "We subsequently investigated whether Clcn3 deficiency affects HFD-induced glucose and lipid metabolism disorders." (PMID 38784133, 2024).
multiple myeloma (1 paper, 2019). "CLCN3 also accelerates the G0/G1 to S phase transition in the cell cycle by enhancing the phosphorylation of ERK1/2 and upregulating cyclin E and cyclin D1 in multiple myeloma cells." (PMID 31608175, 2019).
neuronal ceroid lipofuscinosis (1 paper, 2021). "However, one Clcn3−/− mouse model displayed deposits of the mitochondrial ATP synthase subunit c, typically found in the lysosomal storage disease neuronal ceroid lipofuscinosis (NCL)." (PMID 33708769, 2021).
oral cancer (1 paper, 2024). "In addition, several downstream targets of these specific microRNAs were upregulated by all oral cancer cell lines, such as MBTD1 and FSCN1, or downregulated in all cell lines, such as CLCN3, FLI-1, MRTFB, DAB, SRGAP1, and ABHD17C." (PMID 38396844, 2024).
osteopetrosis (1 paper, 2024). Osteopetrosis, also known as marble bone disease, is a descriptive term that refers to a group of rare, heritable disorders of the skeleton characterized by increased bone density on radiographs. "Moreover, the chloride channels CLCN3 and CLCN7 are known to participate in bone resorption because CLCN7 ablation leads to osteopetrosis in humans and CLCN3 contributes to organelle acidification in mice." (PMID 38395460, 2024).
viral infection (1 paper, 2014). "Our conclusion that ClC-3 restricts glutamate accumulation in SV could be further substantiated by rescuing experiments with Clcn3-/- neurons that express ClC-3 after viral infection." (PMID 24904288, 2014).